ATP9A (ATPase phospholipid transporting 9A)
Description:
Plays a role in regulating membrane trafficking of cargo proteins, namely endosome to plasma membrane recycling, probably acting through RAB5 and RAB11 activation. Also involved in endosome to trans-Golgi network retrograde transport. In complex with MON2 and DOP1B, regulates SNX3 retromer-mediated endosomal sorting of WLS, a transporter of Wnt morphogens in developing tissues. Participates in the formation of endosomal carriers that direct WLS trafficking back to Golgi, away from lysosomal degradation. Appears to be implicated in intercellular communication by negatively regulating the release of exosomes. The flippase activity towards membrane lipids and its role in membrane asymmetry remains to be proved. Required for the maintenance of neurite morphology and synaptic transmission (By similarity).
Synonyms: ATPIIA; KIAA0611; NEDGBA
Tractability: Antibody: UniProt places it where antibodies can reach, with high confidence; its Gene Ontology location is reachable by antibodies, with high confidence; UniProt predicts a signal peptide or a membrane-spanning region. PROTAC: ubiquitination databases record sites on it; its protein half-life has been measured.
Gene: Protein-coding gene on chromosome 20 (51,596,514 to 51,768,390, reverse strand). Ensembl gene ENSG00000054793.
Subcellular location: Early endosome membrane; Recycling endosome membrane; Late endosome membrane; Golgi apparatus, trans-Golgi network membrane; Cell membrane
Pathways (Reactome):
Transport of small molecules: Ion transport by P-type ATPases
Gene Ontology:
Molecular function: protease binding; protein binding; ATP binding; ATP hydrolysis activity; ATPase-coupled intramembrane lipid transporter activity; magnesium ion binding; nucleotide binding
Biological process: negative regulation of exosomal secretion; regulation of endocytic recycling; regulation of retrograde transport, endosome to Golgi; endocytosis; Golgi to endosome transport; neuron projection morphogenesis; phospholipid translocation; retrograde vesicle-mediated transport, Golgi to endoplasmic reticulum; phospholipid transport
Cellular component: early endosome; early endosome membrane; late endosome; late endosome membrane; perinuclear region of cytoplasm; plasma membrane; recycling endosome; recycling endosome membrane; trans-Golgi network; trans-Golgi network membrane; endosome; Golgi apparatus; cytoplasm; cytosol; endomembrane system; membrane
Genetic constraint (gnomAD): Loss-of-function variants: 48 observed, 134.04 expected, observed/expected ratio (o/e) 0.36, 90% interval 0.28 to 0.46. The upper end of that interval is the gene's LOEUF score, 0.46, which puts it in group 2 of 6, group 1 being the genes least tolerant of losing a copy. Missense variants: 913 observed, 1,369.2 expected, observed/expected ratio (o/e) 0.67, 90% interval 0.63 to 0.7. Synonymous variants: 555 observed, 546.55 expected, observed/expected ratio (o/e) 1.02, 90% interval 0.95 to 1.09.
Homologues: Orthologues: macaque ATP9A (99% identical), dog ATP9A (99% identical), mouse Atp9a (98% identical), rat Atp9a (98% identical), chimpanzee ATP9A (96% identical), guinea pig ATP9A (96% identical), tropical clawed frog atp9a (92% identical), pig ATP9A (89% identical), zebrafish ATP9A (84% identical), Drosophila melanogaster CG31729 (62% identical), rabbit ATP9A (58% identical), Caenorhabditis elegans tat-5 (56% identical), and 3 more. Paralogues in human: ATP9B (76% identical), ATP8B2 (32% identical), ATP8B4 (30% identical), ATP10B (30% identical), ATP8B1 (30% identical), ATP11A (30% identical), ATP10A (29% identical), ATP10D (29% identical), ATP11B (29% identical), ATP11C (29% identical), ATP8A2 (29% identical), ATP8A1 (29% identical), and 1 more.
Diseases named in the same sentence as ATP9A in open-access papers:
ATP9A is named in the same sentence as 17 diseases in open-access papers, as found by Europe PMC text mining. Sharing a sentence is not in itself a finding about the gene and the disease. The quoted sentences say what the papers report.
hepatocellular carcinoma (4 papers, 2019 to 2024). A malignant tumor that arises from hepatocytes. "High ATP9A expression levels correlate with poor outcomes for patients with hepatocellular carcinoma." (PMID 38382846, 2024). "In hepatocellular carcinoma cells, ATP9A regulates micropinocytosis to promote nutrient acquisition and also interacts with a V-ATPase subunit (ATP6V1A) to facilitate its endosome to plasma membrane trafficking." (PMID 38382846, 2024). "In hepatocellular carcinoma cells, ATP9A was critical for regulating macropinocytosis via interaction with ATP6V1A resulting in plasma membrane cholesterol accumulation." (PMID 37686603, 2023). "The knockdown expression of ATP9A in human hepatoma cells shows that the elevated release of EVs is independent of the activation of caspase-3." (PMID 33178388, 2020). "We show that knockdown of ATP9A expression in human hepatoma cells resulted in a significant increase in EV release that was independent of caspase-3 activation." (PMID 30947313, 2019). "To investigate whether its mammalian ortholog ATP9A also controls EV release in mammalian cells, we studied the effect of ATP9A knock-down (KD) in the human hepatoma cell line HepG2." (PMID 30947313, 2019).
Intellectual disability (3 papers, 2025). "In humans, ATP9A homozygous recessive mutations cause neurodevelopmental defects leading to postnatal microcephaly, intellectual disability, attention deficit hyperactivity disorder, and hypotonia." (PMID 40093091, 2025). "In this study, we propose a novel mode of inheritance for ATP9A-related disorders with the identification of five de novo heterozygous missense variants (p.(Thr393Arg), p.(Glu400Gln), p.(Lys461Glu), p.(Gly552Ala), and p.(His713Asp)), in patients with intellectual disability." (PMID 40226306, 2025).
nicotine dependence (2 papers, 2014 to 2017). Physical and psychological dependence on nicotine. "Of particular interest were findings in FRMD4A, ATP9A, GALNT2, and MEG3—genes that are implicated in processes related to nicotine dependence, smoking cessation, and placental and embryonic development." (PMID 24906187, 2014). "Thus, if the altered methylation states of FRMD4A and/or ATP9A persisted through adolescence, these could potentially contribute to the observed relationship between maternal smoking and smoking-related traits, such as nicotine dependence, in offspring." (PMID 24906187, 2014).
Azoospermia (1 paper, 2022). Absence of any measurable level of sperm,whereby spermatozoa cannot be observed even after centrifugation of the semen pellet. "In non-obstructive azoospermia, the gene ATPase phospholipid transporter 9A (ATP9A) was upregulated, whereas the ring finger and WD repeat domain 3 (RFWD3) and phosphatidylinositol glycan anchor biosynthesis class K (PIGK) were downregulated." (PMID 36293429, 2022).
breast carcinoma (1 paper, 2019). "To provide evidence for a general role of ATP9A in the release of EVs, we quantified EV numbers in 2 other cell lines of different origin, i.e. the human breast cancer cell line MCF-7 and the human monocytic leukemia cell line THP-1." (PMID 30947313, 2019).
infertile (1 paper, 2020). "It is worth noting that miR-16, a miRNA that was found to be down-regulated in the semen of infertile males with sperm abnormalities, correlated with four sperm phenotypes and potentially interacted with 67 genes (e.g. ATP9A, found in the shared network and included in the RNA model)." (PMID 33292187, 2020).
multiple sclerosis (1 paper, 2022). A progressive autoimmune disorder affecting the central nervous system resulting in demyelination. "Moreover, a variant in ATP9A has been associated with multiple sclerosis in a homozygosity haplotype analysis." (PMID 36517845, 2022). "A further four—ATP9A, TMEM232, PHACTR2 and SLC6A11—out of the seven autoimmune genes identified in this study can also be linked to multiple sclerosis development." (PMID 36517845, 2022).
prostate carcinoma (1 paper, 2020). A carcinoma that arises from epithelial cells of the prostate gland. "Some of the genes associated with these 16 sites included PLEKHA7, AP1M2, ATP9A, and ARVCF known to be downregulated in breast and prostate cancer (data not shown), as well as other cancers." (PMID 32503656, 2020).
substance dependence (1 paper, 2014). The psychological or physiological need to take a substance in order to experience its effects or to avoid the effects of its absence. "We identified altered methylation of CpGs near two genes, FRMD4A and ATP9A, associated with nicotine and substance dependence, and the ability to quit smoking." (PMID 24906187, 2014).
cancer (3 papers, 2018 to 2024). A tumor composed of atypical neoplastic, often pleomorphic cells that invade other tissues. "For non-cancer studies, the miDRB-targeted exosome biogenesis genes for ferroptosis-inhibiting miRNAs are retrieved as follows: miR-19a-3p (SDC1, VPS4B, and MYO5B), miR-424-5p (VPS4A and MYO5B), miR-4291 (ATP9A, SMPD3, TSG101, and MYO5B), miR-522-3p (PDCD6IP), and miR-670-3p (CD34 and RAB27A)." (PMID 38892270, 2024).
neurodevelopmental disorder (2 papers, 2021 to 2025). A behavioral and cognitive disorder with onset during the developmental period that involves impaired or aberrant development of intellectual, motor, or social functions. "They strengthen the association of ATP9A with neurodevelopmental disorders and demonstrate that a double mode of inheritance should be considered for ATP9A-related disorders." (PMID 40226306, 2025). "Here we report two consanguineous families with homozygous pathogenic variants predicted to alter ATP9A splicing and we propose ATP9A as a novel cause of a recessive neurodevelopmental disorder." (PMID 34764295, 2021). "ATP9A (Online Mendelian Inheritance in Man (OMIM)⁣∗609126, NM_006045.3) has recently been added to the list of candidate genes involved in this disorder with the identification of biallelic truncating variants in patients with a neurodevelopmental disorder." (PMID 40226306, 2025).
ATP9A also shares sentences with these, for which no sentence is quoted: attention deficit-hyperactivity disorder (2 papers); microcephaly (2); follicular lymphoma (1); lymphoma (1); monocytic leukemia (1); Sepsis (1).